STIM1 (stromal interaction molecule 1)
Diseases named in the same sentence as STIM1 in open-access papers (continued):
Sharing a sentence is not in itself a finding about the gene and the disease.
anaplastic cancer (1 paper, 2021). "We show here that the protein level of STIM1 is higher in human follicular and anaplastic cancer cell lines, and that ORAI1 is higher in follicular cancer cell lines, compared with normal human thyroid primary cells." (PMID 34155535, 2021).
anaplastic thyroid cancer (1 paper, 2021). "Furthermore, STIM1 was upregulated in all studied patient samples of papillary, follicular, and anaplastic thyroid cancer, compared with healthy thyroid tissues from the same patients or from normal healthy subjects." (PMID 34155535, 2021).
apneic episodes (1 paper, 2023).
asplenia (1 paper, 2025). "The STIM1 gene associated with autosomal-dominant Stormorken syndrome with functional asplenia may be a candidate for further studies." (PMID 41300788, 2025).
Ataxia (1 paper, 2020). Ataxia refers to impaired coordination of voluntary muscle movement. "For example, given that impaired intrinsic plasticity or degeneration of Purkinje neurons is associated with ataxia and STIM1 knockdown is linked to impaired intrinsic plasticity, deficiency of STIM1-mediated SOCE could be a potential cause of ataxia." (PMID 33328896, 2020).
autoimmune encephalitis (1 paper, 2021). Inflammation of the brain secondary to an immune response triggered by the body itself. "For example, knockout of STIM1 and STIM2 or ORAI1, key molecules controlling store operated Ca2+ entry, impaired the differentiation of Th1 and Th17 cells in vitro and in vivo, and protected mice from experimental autoimmune encephalitis." (PMID 34831261, 2021).
autosomal dominant polycystic kidney disease (1 paper, 2021). Autosomal dominant form of polycystic kidney disease. "Another negative regulator of STIM1 is the fragment P100 of polycystin-1, the gene product of PKD1 whose mutations result in autosomal dominant polycystic kidney disease (ADPKD)." (PMID 34685498, 2021).
basophilic leukemia (1 paper, 2020). "To evaluate whether these STIM1 hydrophobic pocket mutants are able to fully activate endogenous store-operated channels, we performed whole-cell patch-clamp experiments in rat basophilic leukemia (RBL) cells." (PMID 32575830, 2020).
bone metastasis (1 paper, 2024). Transfer of a neoplasm from its primary site to bones. "The (CK+/STIM1+/ORAI1+) phenotype was correlated to bone metastasis (p = 0.034), while the (CK+/STIM1+/ORAI1–) to disease relapse (p = 0.049)." (PMID 38903530, 2024). "STIM1 and ORAI1 expression was related to disease recurrence and bone metastasis." (PMID 38903530, 2024).
brain hemorrhage (1 paper, 2020). "Inhibiting CRAC channels with CM‐EX‐137 has been shown to decrease lesion size, brain hemorrhage, and improve neurological deficits while decreasing microglial activation, iNOS, Orai1, and STIM1 levels in an animal model of traumatic brain injury." (PMID 32525239, 2020).
Cachexia (1 paper, 2021). Severe weight loss, wasting of muscle, loss of appetite, and general debility related to a chronic disease. "This leads to different skeletal muscle disorders including muscular hypotonia and myopathies associated to STIM1/ORAI1 mutations, muscular dystrophies, cachexia and sarcopenia." (PMID 34685702, 2021).
Candida infection (1 paper, 2020). "By contrast, T cell‐specific deletion of STIM1 did not result in increased susceptibility to mucosal Candida infection." (PMID 32609955, 2020).
Cerebral ischemia (1 paper, 2019). Restriction of arterial blood supply to the brain associated with insufficient oxygenation to support the metabolic requirements of the tissue. "Moreover, mouse STIM1-deficient platelets were protected from neuronal damage after temporary cerebral ischemia." (PMID 31075835, 2019).
cerebrovascular disease (1 paper, 2020). "Creation of the congenic SHR-A3(Stim1-B2) line demonstrates that rescue of defective Stim1 function prevents development of cerebrovascular disease in SHR-A3 while restoring T helper cell functions." (PMID 32300198, 2020). "We have also examined the emergence of cerebrovascular disease in the Stim1-rescued SHR-A3 line and compared it with SHR-A3." (PMID 32300198, 2020).
chlamydia infection (1 paper, 2022). "Re-analysis of the data from Dzakah41 revealed that none of the isoforms of STIM1 or Orai1 were significantly up- or down-regulated at 20 h post chlamydia infection." (PMID 36496532, 2022).
chorea-acanthocytosis (1 paper, 2017). Chorea-acanthocytosis (ChAc) is a form of neuroacanthocytosis and is characterized clinically by a Huntington disease-like phenotype with progressive neurological symptoms including movement disorders, psychiatric manifestations and cognitive disturbances. "In order to test whether the pathophysiology of chorea-acanthocytosis (ChAc) involves deranged neuronal regulation of the Ca2+ release activated Ca2+ channel ORAI1 and/or its regulator STIM1, experiments were performed with neurons generated from induced pluripotent stem cells (iPSCs)." (PMID 28743945, 2017).
chronic myeloid leukemia (1 paper, 2020). "Since the first proof of concept trial for stopping tyrosine kinase inhibitors (TKIs), the STIM1 study, successful treatment-free remission (TFR) has been obtained in many patients with chronic-phase chronic myeloid leukemia (CP-CML), both after imatinib and after second generation TKIs (2GTKIs)." (PMID 33213044, 2020).
coronary artery disease (1 paper, 2022). "For example, it has been shown that a variant upstream of STIM1, named rs3061890, has been associated with coronary artery disease and has been shown to repress STIM1 in an ELF1-dependent manner." (PMID 35821821, 2022).
Cough (1 paper, 2022). A sudden, audible expulsion of air from the lungs through a partially closed glottis, preceded by inhalation. "Herein, we describe a patient with TAM/STRMK due to a novel L303P STIM1 mutation, who not only presented clinical manifestations characteristic of TAM/STRMK but also manifested immunological involvement with respiratory infections since childhood, with chronic cough and chronic bronchiectasis." (PMID 35812399, 2022).
cyst (1 paper, 2025). A sac-like closed membranous structure that may be empty or contain fluid or amorphous material. "Recent research has shown that elevated levels of STIM1 and IP3R contribute to cyst growth by increasing the cAMP levels and promoting Ca+2 release from the ER, as demonstrated using STIM1 knockdown and pkd1 knockout in an ADPKD mouse model compared to non-cystic controls." (PMID 40136708, 2025).
desminopathies (1 paper, 2021). "Disruption of the link between STIM1 and desmin may alter STIM1-Ca2+ signaling and contribute to the muscle degeneration and weakness associated with desminopathies." (PMID 34494555, 2021). "Strategies designed to regulate the desmin-STIM1 interaction may serve as an exercise mimetic or as therapy for desminopathies." (PMID 34494555, 2021).
diabetic cardiomyopathy (1 paper, 2023). Diabetic cardiomyopathy is a disorder of the heart muscle in people with diabetes. "Of note, the metabolic changes caused by STIM1 deficiency in cardiomyocytes are similar to those in a heart suffering from diabetic cardiomyopathy." (PMID 37685995, 2023). "Nevertheless, it is difficult to distinguish if these changes of the key proteins for glucose utilization in diabetic cardiomyopathy are from a direct effect of STIM1 deficiency or a secondary effect of lipid accumulation caused by STIM1 deficiency." (PMID 37685995, 2023). "It would be intriguing to test if there is a link between STIM1 and GSK-3α activity (Figure 5➁), which would provide more insights on the mechanisms by which STIM1 regulates FA metabolism in diabetic cardiomyopathy." (PMID 37685995, 2023). "How increased FA influences STIM1 expression in diabetic cardiomyopathy still needs to be determined." (PMID 37685995, 2023). "Results showed that the PDK4-dependent decrease in glucose oxidation in diabetic cardiomyopathy is likely due to lipid accumulation instead of lower STIM1 expression." (PMID 37685995, 2023). "In addition, the relationship between STIM1 and altered glucose metabolism in diabetic cardiomyopathy will also be discussed." (PMID 37685995, 2023). "This phenomenon indicates that decreased STIM1 in the development of diabetic cardiomyopathy may increase the CPT1 expression and corresponding FA oxidation rate." (PMID 37685995, 2023). "Therefore, increased lipid accumulation in diabetic cardiomyopathy could cause more S-acylation of STIM1 and thus increase SOCE to some extent, acting as feedback to rescue decreased STIM1 expression-induced SOCE reduction (Figure 5➅)." (PMID 37685995, 2023). "Although it is believed that decreased glucose consumption is a result of lipid accumulation in diabetic cardiomyopathy, the reduction in STIM1 could also contribute to the decrease in glucose utilization by downregulating GLUT4 expression in diabetic cardiomyopathy." (PMID 37685995, 2023). "Therefore, we propose that instead of influencing CD36 expression, decreased STIM1 expression in diabetic cardiomyopathy could increase FA uptake by the relocation of CD36 to the sarcolemma through the inactivation of the AKT–mTORC1–v-ATPase signaling pathway (Figure 5➀)." (PMID 37685995, 2023).
diabetic kidney disease (1 paper, 2017). Progressive kidney disorder caused by vascular damage to the glomerular capillaries, in patients with diabetes mellitus. "The cycling of ion channel complexes through clathrin-coated vesicles has important implications in the pathophysiology of diabetic kidney disease and may also be related to the disease processes of ORAI1/STIM1 mutations." (PMID 29203863, 2017).
dystrophin deficiency (1 paper, 2021). "In conclusion, SOCs are major contributors to dystrophin deficiency-dependent Ca2+ overload through STIM1–Orai1 as molecular mediators." (PMID 34829817, 2021).
Ebola (1 paper, 2025). "The activation of the STIM1 and Orai1 channels promotes virion assembly and budding during Ebola or Marburg virus infection." (PMID 40626726, 2025).
endometrial cancer (1 paper, 2018). Primary or metastatic malignant neoplasm involving the endometrium (mucous membrane that lines the endometrial cavity). "It is noteworthy that ORAI1/STIM1 is upregulated by the serum and glucocorticoid inducible kinase (SGK1) and TGF-β in endometrial cancer cells, but downregulated by the AMP activated kinase (AMPK)." (PMID 29230527, 2018).
fatty liver disease (1 paper, 2023). A reversible condition wherein large vacuoles of triglyceride fat accumulate in liver cells via the process of steatosis. "STIMATE encodes a store-operated Ca2+ junction regulator that indirectly interacts with the STIM1 calcium channel regulatory protein, whose dysfunction is related to fatty liver disease." (PMID 37859957, 2023).
glaucoma (1 paper, 2024). Increased pressure in the eyeball due to obstruction of the outflow of aqueous humor. "Although there is currently no direct evidence linking STIM1/2 with glaucoma, TRPC1 and TRPC6 channels, which are known interacting partners of STIM isoforms, were upregulated in glaucomatous lamina cribrosa leading to NFAT4-mediated gene expression remodeling." (PMID 39424970, 2024).
Glucose intolerance (1 paper, 2017). Glucose intolerance (GI) can be defined as dysglycemia that comprises both prediabetes and diabetes. "Additionally, mice with acute liver deletion of STIM1 displayed systemic glucose intolerance." (PMID 29243589, 2017).
hyperphosphatemia (1 paper, 2021). Abnormally high level of phosphate in the blood. "In vascular smooth muscle cells, the effect of hyperphosphatemia on ORAI1/STIM1 expression and SOCE is suppressed by Mg2+ and the calcium-sensing receptor (CaSR) agonist Gd3+." (PMID 33804889, 2021).
hypersensitivity pneumonitis (1 paper, 2016). Hypersensitivity pneumonitis (HP) is a pulmonary disease with symptoms of dyspnea and cough resulting from the inhalation of an antigen to which the subject has been previously sensitized. "Neutrophil emigration was reduced by both Orai1 and Stim1 deletion in a hypersensitivity pneumonitis model that uses an immune complex-mediated reaction involving the release of chemoattractants by alveolar macrophages, which itself was normal in Orai1−/− and reduced in Stim1−/− chimeric mice." (PMID 26764049, 2016).
Hypokalemia (1 paper, 2022). An abnormally decreased potassium concentration in the blood. "However, hypokalemia is often also associated with changes in the p wave, which we do not observe in our crSTIM1−/− hearts and is consistent with previous reports in mouse models of STIM1 deficiency." (PMID 35179826, 2022). "It is possible that hypokalemia could contribute since in crSTIM1−/− hearts we observe these same changes, and several potassium channels that mediate cardiac repolarization were identified as downstream peptide targets of STIM1 in the kinomic analysis." (PMID 35179826, 2022).
Immunodeficiency 10 (1 paper, 2023). "Immunodeficiency 10 is due to a homozygous truncating variant in the STIM1 gene." (PMID 37228816, 2023).
ischemic stroke (1 paper, 2022). A stroke disorder caused by obstruction of blood flow to the brain, due to thrombotic (local blood clot formation) or embolic (due to a blood clot or other material traveling from another site) event. "In addition, when compared to wild-type littermates, STIM1-deficient chimeric mice showed a substantially reduced infarct size and a better neurological outcome without intracranial hemorrhages in a transient middle cerebral artery occlusion (tMCAO) mouse model of ischemic stroke." (PMID 35203269, 2022). "Although 2-APB protects from severe ischemic stroke in a mouse model of tMCAO and was described to interfere with the STIM1/Orai1 coupling, the underlying mechanism is not well-defined and most likely includes additional processes that are independent of SOCE signaling in platelets." (PMID 35203269, 2022).
Kawasaki disease (1 paper, 2024). A rare inflammatory disease characterized by an acute febrile, systemic, self-limiting, medium-vessel vasculitis primarily affecting children. "Finally, taking into consideration the causal associated between ITPKC polymophisms and Kawasaki disease, we have noted that overexpression of ITPKC in lung fibroblasts results in enhanced T cell activation (ORAI1, STIM1), which is associated with Kawasaki disease." (PMID 38991987, 2024).
left ventricular hypertrophy (1 paper, 2019). Enlargement of the LEFT VENTRICLE of the heart. "In this context, TRPCs (canonical transient receptor potential channels)-, STIM1 (stromal interaction molecule 1)-, and Orai1-dependent Ca2+ entry are instrumental for pathological left ventricular hypertrophy development." (PMID 30988334, 2019).
lymphoma (1 paper, 2022). A malignant (clonal) proliferation of B- lymphocytes or T- lymphocytes which involves the lymph nodes, bone marrow and/or extranodal sites. "Interestingly, the pairwise cell line analysis did not indicate any significant differences in expression level for STIM1/2, suggesting that ER Ca2+ sensing might not vary to a great extent across different types of lymphoma, although this would require further investigation." (PMID 35685639, 2022).
lymphoproliferative disorder (1 paper, 2024). "Mice deficient in both Stim1 and Stim2 in T cells develop a lymphoproliferative disorder with markedly increased number of splenic TFH cells and diminished TFR cells in secondary lymphoid organs." (PMID 38578569, 2024).
metastatic prostate carcinoma (1 paper, 2024). A carcinoma that arises from the prostate gland and has spread to other anatomic sites. "Discussion: STIM1, ORAI1, and KDM2B were overexpressed in CTCs from patients with metastatic prostate cancer." (PMID 38903530, 2024). "Statistical analysis revealed that the presence of (CK+/STIM1+/ORAI1–) phenotype significantly related (Spearman’s rho analysis, p = 0.049) with relapse in metastatic prostate cancer patients." (PMID 38903530, 2024). "Since CTCs are the major players in metastasis in the current study, we investigated for the first time the expression of STIM1, ORAI1, and KDM2B simultaneously in Circulating Tumor Cells from the same blood draw of metastatic prostate cancer patients." (PMID 38903530, 2024).
microphthalmia (1 paper, 2023). Congenital or developmental anomaly in which the eyeballs are abnormally small. "A similar search of DR17 using the term microphthalmia resulted in 22 genes significant for the small eyes phenotype: Aldh1a3, Aff4, Bmp4, Cdk4, Cox6b1, Cxcr4, Dync1li1, Eef1d, Fgd1, Gne, Grh12, Mab21l2, Maf, Med13l, Mllt10, Mthfd2, Pex6, Phgdh, Ssr1, Stim1, Tdo2, and Vps26c." (PMID 36737727, 2023).
muscle atrophy (1 paper, 2024). The loss of muscle tissue due to inactivity or disease. "The clinical syndrome of muscle atrophy and weakness develops in humans as a result of gain-of-function mutations in the STIM1 and ORAI1 genes." (PMID 38300705, 2024).
neuralgia (1 paper, 2024). "This discovery reveals one of the pathological mechanisms of trigeminal neuralgia, namely that STIM1, by regulating SOCE, further affects the release of inflammatory factors in T lymphocytes, thereby influencing the occurrence of neuralgia." (PMID 38962804, 2024).
onychomycosis (1 paper, 2020). "The patients with STIM1 p.L374P mutation reported here presented with severe onychomycosis." (PMID 32609955, 2020).
overactive bladder (1 paper, 2022). Symptom of overactive detrusor muscle of the urinary bladder that contracts with abnormally high frequency and urgency. "Compared to the model, OCP50, CP100, and OCP100 relieved the overactive bladder and inhibited the expression of Orail and STIM1." (PMID 35832402, 2022). "Finally, in this research, we found that the oxybutynin hydrogel could affect the expression of Orail and STIM1 and change the intracellular calcium concentration to improve the progression of the overactive bladder, which provided new methods for the treatment of OAB." (PMID 35832402, 2022).
parasite infection (1 paper, 2009). "In addition to strong expression of IFNβ and CCL5 in all cell types, parasite infection induces the expression of genes involved in cell-matrix interactions (osteopontin; SPP1) carbohydrate modification (B4GT5 and B3GNT2), vesicular transport SYTL3 and T-SNARE1 and Ca2+ homeostasis STIM1 and CARKL." (PMID 19480704, 2009).
pulmonary fibrosis (1 paper, 2022). Chronic progressive interstitial lung disorder characterized by the replacement of the lung tissue by connective tissue, leading to progressive dyspnea, respiratory failure, or right heart failure. "The herbicide paraquat is an agonist of Stromal Interaction Molecule 1 (STIM1), leading to extracellular calcium entry observed in epithelial-mesenchymal transition in alveolar cells during pulmonary fibrosis." (PMID 36310238, 2022).
rosacea (1 paper, 2025). A chronic erythematous skin disorder that affects the face. "Also, the increased STIM1 expression may be contributed by keratinocytes and other structural cells within the rosacea mice rather than being exclusively associated with MCs." (PMID 41296102, 2025).
Rotavirus infection (1 paper, 2023). Infection with any of the rotaviruses. "Rotavirus NSP4 is an important factor in the depletion of ER Ca2+ by activation of STIM1 and ORAI, indicating that inhibition of STIM1 and ORAI can inhibit the rotavirus infection." (PMID 37700758, 2023).
T-cell ALL (1 paper, 2019). "Lastly, a recent report found that stromal interaction molecule 1 (STIM1) and STIM2 mediated the pathologic cancer-induced inflammation in the TME of T-cell ALL." (PMID 31783588, 2019).